NRP1 (neuropilin 1)
Diseases named in the same sentence as NRP1 in open-access papers (continued):
Sharing a sentence is not in itself a finding about the gene and the disease.
breast carcinoma (continued). "Similarly, another clinical study showed that NRP-1 protein concentrations in breast cancer tissue were significantly higher in patients with lymph node metastasis." (PMID 37175499, 2023). "Additionally, FN1 which is an ECM remodeling-related molecule was downregulated in the NRP-1 KO cells and was shown to play a key role in breast cancer stroma invasion and metastasis." (PMID 37175499, 2023). "Furthermore, we showed that ectopic NRP-1 overexpression in BT-474 breast cancer cells promoted their in vitro pro-tumorigenic behavior." (PMID 37175499, 2023). "The vast majority (up to 88%) of neuropilin-1+ cells proximal to the panobinostat well were cytotoxic neutrophils, suggesting neuropilin-1 as a novel biomarker of anti-tumor neutrophils in breast cancer—a hypothesis that remains to be functionally tested." (PMID 35788566, 2022). "Our previous studies demonstrated that NRP-1 acts as an oncogene in breast cancer progression." (PMID 34374639, 2022). "Recent studies revealed that NRP-1 could promote breast cancer cells resistance to ADM and PTX resistance through activation of ITGB3/FAK/NF-kB p65 axis and downregulation of BCRP/ABCG2." (PMID 34374639, 2022). "Suppression of NRP1 expression by JQ1 has already been shown in breast cancer cells." (PMID 36231049, 2022). "In particular, high levels of NRP1 were associated with chemoresistance in breast cancers having negative prognostic correlations." (PMID 35887839, 2022). "Meanwhile, we determined the expression of NRP-1 in chemoresistant breast cancer cells and tissues." (PMID 34374639, 2022). "To assess whether NRP1 expression has utility as a prognostic marker of BrCa outcome, we utilized the TCGA breast cancer dataset." (PMID 35078508, 2022). "Moreover, we observed a significant inverse correlation between FOXO3a and VEGF-A/NRP1 expression levels, and a significant positive correlation between VEGF-A and NRP1 in the breast cancer tissues." (PMID 33262463, 2021). "Therefore, we propose that a reduction in miR-29b/miR-338 expression elicited by FOXO3a inactivation results in alleviation of miR-29b/miR-338-mediated targeting of VEGF-A/NRP1, thus contributing to the aggressive behavior of breast cancers." (PMID 33262463, 2021). "Collectively, our findings propose that FOXO3a functions as a metastasis suppressor, and define a novel signaling axis of FOXO3a-miRNA-VEGF-A/NRP1 in breast cancer, which might be potential therapeutic targets for breast cancer." (PMID 33262463, 2021). "Together with the known drawbacks of targeting VEGF signaling in metastatic breast cancer, our findings may, in part, serve to explain the clinical inability of NRP1 antibody blockade to effectively inhibit metastatic tumor progression." (PMID 33128042, 2021). "demonstrated, using a CSC KO model for NRP1 or VEGF-A, that this signaling axis was necessary to ensure the specific traits of CSCs in vitro and in vivo, and that the VEGF-A/NRP1 axis conferred the strain phenotype to breast cancer cells by activating the WNT/β-catenin signaling pathway." (PMID 34277411, 2021). "In the past years, the role of NRP-1 in cancer progression has gained significant interest with studies showing a tumor promoting or prognostic role in several malignancies including pancreas, liver, gastric, colon, lung and breast cancer." (PMID 33884469, 2021). "To demonstrate the role of miR-29b-2 and miR-338 in the FOXO3a-mediated repression of VEGF-A/NRP1 and breast cancer metastasis, we determined whether the FOXO3a-mediated repression of VEGF-A/NRP1 can be reversed by knockdown of miR-29b-2 and miR-338." (PMID 33262463, 2021). "This suggests a role for NRP1-mediated FGFR signaling in breast cancer progression and EMT." (PMID 34068954, 2021). "In addition, we found that FOXO3a-driven miR-29b/miR-338 expression plays a critical role in the posttranscriptional regulation of VEGF-A/NRP1 signaling and breast cancer metastasis." (PMID 33262463, 2021).
breast carcinoma (continued). "Therefore, NRP1 overexpression is described as a poor prognostic factor in various cancers, such as lung cancers, pancreatic cancers, liver cancers, breast cancers, gliomas, and medulloblastomas." (PMID 34277411, 2021). "As a new member of the FOXO3a regulatory network, miR-29b/miR-338 may play a critical role in the posttranscriptional regulation of the VEGF-A/NRP1 axis and breast cancer metastasis." (PMID 33262463, 2021). "The inhibition curves suggest a reduced neutralisation efficiency in the CAL-51 breast cancer cell line, which might be attributed to NRP-1-mediated or NRP-1-assisted virus entry." (PMID 34339474, 2021). "Similarly, ectopic expression of miR-338 also significantly suppressed the mRNA and protein expression of NRP1 in breast cancer cells." (PMID 33262463, 2021). "Furthermore, the VEGF/NRP1 pathway induces CSCs in breast cancers by activating the Wnt/β-catenin pathway, which is involved in the induction of CSCs." (PMID 32766254, 2020). "Likewise, NRP1 gene silencing was reported to suppress the proliferation, promote apoptosis and increase the sensitivity of breast cancer cells (i.e., MCF-7, SK-BR-3) to chemotherapy." (PMID 33121034, 2020). "Likewise, the VEGF-A/NRP1 axis was suggested to confer cancer stem cell traits in breast cancer cells (i.e., MCF-7, MDA-MB-231) by activating the Wnt/β-catenin pathway." (PMID 33121034, 2020). "Indeed, NRP1-targeting proved effective to prevent the onset of drug-resistance or restore responsiveness to oncogene-targeted therapies in melanoma and breast cancer preclinical models." (PMID 31027288, 2019). "Also by downregulating NRP1 levels, miR-376a inhibits in breast cancer cells the Wnt/β-catenin signaling axis and, thus, proliferation, migration, and invasion, and it promotes apoptosis." (PMID 30717262, 2019). "Alternative mechanism to engage with other cell types to mediate adhesion and transendothelial migration include ALCAM, which allows breast cancer cells to interact with endothelium, and NRP-1, which is involved in the interaction of ovarian cancer cells with the mesothelium." (PMID 31455004, 2019). "A comprehensive analysis of NRP-1 expression in human cancer (consisting of 65 primary breast carcinomas, 95 primary colorectal adenocarcinomas, 90 primary lung carcinomas, and 59 metastases) in 98–100% of all the tumor sections, overexpression of NRP-1 was observed in the tumor-associated vessels." (PMID 33568892, 2019). "NRP1 on breast cancer cells binds both latent and active TGF-β1 with high affinity." (PMID 30717262, 2019). "Therefore, in this study, we explored the effect of NAC on the levels of plasma and tissue NRP-1 and PlGF, as well as validating their use as predictive/pharmacodynamic breast cancer biomarkers." (PMID 31106153, 2019). "Remarkably, the treatment combination with NRP1-interfering molecules improved the efficacy of oncogene-targeted drugs and prevented the onset of resistance (or even reversed it) in multiple tumor models, like melanoma, lung and breast cancer cells." (PMID 31027288, 2019). "iRGD contains an αv-integrin-binding motif and an RGDK cryptic CendR motif that upon proteolytic activation mediates binding to neuropilin-1 (NRP-1) that is overexpressed and correlates with increased aggressiveness in several solid tumor types, including breast cancer." (PMID 31812165, 2019). "Therefore, the main objectives of this study were to understand novel functional mechanism by which NRP-1 enhances breast cancer progression and to investigate the relationship of NRP-1 with acquired chemoresistance." (PMID 29728077, 2018). "Although increased NRP-1 expression in wild-type BT-474 4xAC cells is associated with lower expression of ABCG2, these cells display a more resistant phenotype, thus indicating that NRP-1 is a more predictive marker of chemoresistant breast cancer than ABCG2." (PMID 29728077, 2018).
breast carcinoma (continued). "VEGF-A activates Akt through NRP1 by an autocrine mechanism to promote breast cancer cell survival." (PMID 29659486, 2018). "Moreover, we highlight the functional role NRP-1 plays in breast cancer resistance by attenuating ABCG2." (PMID 29728077, 2018). "Hence, our observations of the NRP-1 profile in plasma, tissue and PBMCs in breast cancer highlight its multiple roles depending on the cell type." (PMID 28607365, 2017). "Over-expression of Nrp1 (Neuropilin 1), a vascular endothelial cell growth factor (VEGF) 165 Receptor, has been implicated in the vascularization and metastasis of many cancer types, including breast cancer." (PMID 28632792, 2017). "Knockdown of Nrp1 expression in MMTV-Wnt1 inhibited the growth of mammary tumors." (PMID 28887477, 2017). "In the present study, we decided to explore whether targeting NRP1 with our peptide potentially is also suitable for blocking breast cancer growth and metastasis." (PMID 27351129, 2016). "Moreover, the anti-NRP-1B antibody was found to directly inhibit breast cancer cell proliferation, adhesion to fibronectin and formation of NRP-1/α5β1 integrin complexes, as well as phosphorylation of FAK and p130cas." (PMID 26090340, 2015). "Thus, GPNMB and NRP-1 must have an important role in mammary tumor growth and metastasis mediated by α5β1 integrin." (PMID 26558271, 2015). "The sustained NRP-1 expression under prolonged periods of hypoglycemia in the breast cancer cells used here suggests that this protein may play an important albeit different role in these cells as compared to EOC cells." (PMID 25401697, 2014). "Intriguingly C100, a breast cancer cell line that expresses both Nrp1 and Nrp2, responds to exogenous Sema3f with inhibition of cell spreading, and this response is insensitive to the addition of anti-Nrp1 functional blocking antibody." (PMID 22783168, 2012). "The frequency of tumors with Nrp2+ tumor cells was comparable to Nrp1 in breast cancer and NSCLC." (PMID 22948112, 2012). "One such study demonstrated that VEGF acted as an autocrine survival factor for NRP-1-expressing breast cancer cells, protecting them from hypoxia-induced apoptosis in the absence of VEGFR-2 expression through activation of the phosphatidylinositol 3′-kinase pathway." (PMID 15956974, 2005). "In addition to breast cancers, between 40 and 50% of pancreatic tumors have elevated NRP-1 levels." (PMID 39683699, 2024). "Notably, Nrp2 high macrophages lacked Nrp1 expression, suggesting that Nrp2 and Nrp1 are associated with discrete macrophage populations in breast cancer MPEs." (PMID 38592275, 2024). "Moreover, plasma NRP1 levels have been suggested as a valuable biomarker in breast cancer patients." (PMID 35884516, 2022). "Notably, the rescue experiments showed that both miR-6736-3p inhibitor and NRP-1 overexpression could partly reverse the suppressive influence of RP11-70C1.3 knockdown on breast cancer chemoresistance." (PMID 34374639, 2022). "Moreover, NRP-1 and miR-6736-3p were negatively correlated in breast cancer tissues." (PMID 34374639, 2022). "Similarly, TAM subsets within murine mammary tumors or MPEs from breast cancer patients expressed predominantly NRP1 or NPR2Total/NRP2b by flow cytometry, suggesting that expression of NRP1 or NRP2Total/NRP2b on TAMs is associated with non-redundant functions in the breast cancer TME." (PMID 35651620, 2022). "Indeed, NRP1, expressed on the surface of breast cancer tumor cells, allows the internalization of neutrophil elastase, which results in the cross-presentation of the PR1 antigen and which is necessary for the specific lysis of tumor cells by cytotoxic T lymphocytes." (PMID 34277411, 2021). "However, it’s unknown what upstream mRNAs regulate NRP-1 expression in breast cancer, especially TNBC." (PMID 33912463, 2021).
breast carcinoma (continued). "Moreover, VEGF-A/NRP-1 interaction promotes stemness properties in breast cancer (BC) cell lines by activation of Wnt/β-catenin pathway, since its inhibition relies in the attenuation of HUVEC-tube formation induced by co-culturing with extracts from Breast Cancer Stem Cells (BCSCs)." (PMID 32296643, 2020). "Furthermore, inhibition of Nrp1 attenuated MMTV-Wnt1 mammary tumor growth." (PMID 28887477, 2017). "In addition, over-expression of VEGF189 in breast cancer cells induced apoptosis via NRP-1." (PMID 25119572, 2014). "Indeed, Nrp1 or Nrp2 expression is significantly associated with poor survival in breast cancer, independent of other standard prognostic factors." (PMID 22948112, 2012). "The iRGD peptide specifically binds to integrin αvβ3 and neuropilin-1 (Nrp1) receptors overexpressed on tumor cells, leading to a 2.3-fold increase in cellular uptake in MDA-MB231 breast cancer cells." (PMID 40978472, 2025). "Another study targeted the NRP1/TGB3 axis, a novel mechanism in breast cancer cell line BT-474 correlating high NRP1 with TNC/ITGβ3 signaling but decreases the ABCG2 expression, thereby sensitizing BT-474 NRP1 cells to Adriamycin/cyclophosphamide." (PMID 40277760, 2025). "NRP1 has been shown to be highly expressed in different cancer types and together with FSTL1 is predicted to be driver for basal-like breast cancer by DMA." (PMID 40258059, 2025). "It regulates migration and invasion in breast cancer through MyoGEF–Cdc42–MMP9 signaling, facilitates ECM remodeling via interactions with neuropilin-1 and α5β1 integrin, and sustains receptor trafficking in glioma and melanoma." (PMID 41155969, 2025). "Previous studies have confirmed that FOXO3a functions as a tumor suppressor gene in breast cancer, inhibiting VEGF-A/NRP1 signaling and breast cancer metastasis by driving miRNA signatures." (PMID 38566092, 2024). "Our findings suggest that plasma NRP-1 and PlGF are useful in evaluating the prognosis of patients with advanced HER2-negative breast cancer receiving bevacizumab and taxane." (PMID 38468231, 2024). "NRP1 exerts pleiotropic roles in TGF-β signaling, where it activates TGF-β signaling in stromal fibroblast cell lines and breast cancer cells." (PMID 38916960, 2024). "In contrast, induction of NRP1 over expression promotes the proliferation, migration, and invasion of MCF-7 breast cancer cells." (PMID 37894289, 2023). "Combined knockdown of NRP-1 and VEGF inhibits the proliferation, migration, and invasion while enhancing the apoptosis of MDA-MB-231 human breast cancer cells." (PMID 37894289, 2023). "Consistent with this possibility, a subpopulation of breast cancer cells expressing CSC markers also express NRP1, and an anti-NRP1 antibody inhibits the formation of breast CSC-enriched tumorspheres." (PMID 37894289, 2023). "To explore the effect of NRP-1 knockout on the tumorigenic potential of these breast cancer cells, we next performed orthotopic xenograft analysis comparing tumor growth and the metastatic behavior of parental MDA-MB-231, NRP-1 KO, and NRP-1 KO rescued cells." (PMID 37175499, 2023). "Although several previous studies have reported anti-tumorigenic effects of targeting NRP-1 in different types of cancer, we are unaware of any reports on the involvement of NRP-1 in breast cancer metastasis to the lungs." (PMID 37175499, 2023). "Finally, this report emphasized the importance of NRP-1 targeting with a new direction focusing on ECM proteins in treating metastatic breast cancer, which might aid not only in reducing the ability of the cells to metastasize but also in making them more susceptible to treatment." (PMID 37175499, 2023). "Adaptative NRP1 expression is observed in melanoma cells after treatment with BRAF inhibitors and in breast cancer cells treated with HER2 inhibitors, resulting in an acquired resistance to therapy." (PMID 37894289, 2023).
breast carcinoma (continued). "NRP1 expression is increased by glycoprotein NMB (GPNMB), and NRP1 and GPNMB cooperate to stimulate mammary tumor growth." (PMID 37894289, 2023). "In a similar manner, we assessed the impact of codepleting endothelial NRP1 and NRP2 on a luminal B model of breast cancer." (PMID 36970722, 2022). "TAM subsets with high NRP1 co-expressed increased levels of CSF1R and decreased Ly-6C, indicating that NRP1 and NRP2 likely demark unique TAM subsets within murine mammary tumors." (PMID 35651620, 2022). "NRP1 acts as a Neutrophil elastase (NE) receptor mediating uptake and PR1 cross-presentation in breast cancer cells." (PMID 33805666, 2021). "In the current study, we demonstrate that FOXO3a is downregulated in breast cancer, and overexpression of FOXO3a suppresses VEGF-A/NRP1 signaling and breast cancer invasion and metastasis." (PMID 33262463, 2021). "NRP1 exerts coreceptor function for LAP-TGF-β by binding the Glycoprotein A repetitions predominant, which links to poor tumor immunity, in breast cancer." (PMID 33987449, 2021). "There is also evidence showing that FOXP3 suppresses angiogenesis by inhibiting VEGF expression in breast cancer, and on T regulatory cells, FOXP3 contributes to immunosuppression in a NRP1-dependent manner." (PMID 34249735, 2021). "NRP1 forms a complex with FGFR1 in the cytoplasm, which increases during EMT in HER2+ drug-resistant breast cancer cells." (PMID 34068954, 2021). "In most of the cell lines representative of aggressive ccRCC and breast cancers, VEGFA and NRP1 are expressed at high levels especially in the cell lines used in our respective experimental tumor growth (786-O and MDAMB231)." (PMID 33461580, 2021). "Specifically, neuropilin-1 (NRP1), a coreceptor of VEGF-A, forms complexes with VEGFRs to enhance the binding of VEGF-A to VEGFRs, thus promoting VEGF-A-mediated breast cancer cells EMT and metastasis." (PMID 33262463, 2021). "In HER2-positive breast cancer cells with EMT, resistance to HER2 inhibitor was mediated by increased expression and direct interaction of FGFR1 and neuropilin-1 (NRP1)." (PMID 34830951, 2021). "A distinct population of Nrp1+ Treg cells, characterized by CD4+CD25highFoxp3+, was present in mammary tumors of MMTV-PyVT mice treated with adiponectin-expressing EGFP+ cells." (PMID 33727658, 2021). "miR-206 has been found to inhibit autocrine production of TGF-β and downstream neuropilin-1 (NRP1) and SMAD2 expression, leading to decreased migration, invasion, and EMT in breast cancer cells." (PMID 35006436, 2020). "Hence, linc-OIP5 in MDA-MB-231 breast cancer cells may act on the upstream of the YAP1/Notch/NRP1 signaling circuit to affect proliferation, migration, and tube formation of co-cultured HUVECs in a non-cellular direct contact way through JAG1 in conditioned medium." (PMID 32046779, 2020). "NRP1-dependent JNK signaling leads to the overexpression of EGFR and IGF1R, which induces resistance to BRAF (melanoma targeted therapy), HER2 (breast cancer targeted therapy) and MET (stomach and lung carcinomas therapy) inhibitors." (PMID 32766254, 2020). "In breast cancer, binding of VEGF to neuropilin enhanced cancer cell survival with additional evidence showing that NRP1 supports VEGF autocrine invasive function and chemotaxis of breast cancer cells." (PMID 33121034, 2020). "Lastly, we found that NRP1, NRP2, PLXNA1, C1, and D1 had the highest correlation with the expression of immune checkpoint molecules PD1/PDL1 and CTLA-4 in breast cancer." (PMID 32640719, 2020). "In breast cancer, the VEGF-A/Neuropilin 1 pathway promoted cancer stemness by activating Wnt/β-Catenin axis, resulting in cancer stem cell phenotypes and chemoresistance." (PMID 31552163, 2019). "Other research has shown that miR-206 inhibits autocrine production of TGF-β as well as downstream neuropilin-1 (NRP1) and SMAD2 expression, resulting in decreased migration, invasion, and EMT in breast cancer cells." (PMID 31195692, 2019).